ATM (ATM serine/threonine kinase)
Diseases named in the same sentence as ATM in open-access papers (continued):
Sharing a sentence is not in itself a finding about the gene and the disease.
Autoimmunity (5 papers, 2017 to 2025). The occurrence of an immune reaction against the organism's own cells or tissues. "On the other hand, ATM/Chk2 pathway is of interest in B cell autoimmunity because it has been recently reported to drive B cell pathogenicity in a group of patients with RA exhibiting severe disease." (PMID 36306362, 2022). "Moreover, cells derived from AGS patients exhibit chronic ATM-dependent checkpoint activation of cell cycle, connecting this finding to autoimmunity and inflammation." (PMID 39871364, 2025). "In patients with ATM mutation, the IgG level was significantly lower in patients with autoimmunity than in those without (P < 0.001)." (PMID 36790564, 2023). "A comprehensive comparison in terms of demographic, clinical, and immunological features was performed between patients with and without autoimmunity and also among four mutation groups with the most registered cases including ATM, STAT3 (AD-LOF), DNMT3B/ZBTB24, and WAS mutations." (PMID 36544766, 2022). "In contrast, patients with ATM defects who had autoimmunity had a higher level of IgM compared to those without autoimmunity (P = 0.040)." (PMID 36790564, 2023).
cholangiocarcinoma (5 papers, 2020 to 2025). A carcinoma that arises from the intrahepatic biliary tree (intrahepatic cholangiocarcinoma) or from the junction, or adjacent to the junction, of the right and left hepatic ducts (hilar cholangiocarcinoma).
differentiated thyroid carcinoma (5 papers, 2013 to 2015). Differentiated thyroid carcinoma (DTC), also known as papillary or follicular thyroid carcinoma, is a slow-growing malignancy usually presenting in adults as an asymptomatic thyroid mass. "We assessed the contribution of polymorphisms at the 9q22.33 and 14q13.3 loci identified by GWAS, and within the DNA repair gene ATM, to the risk of differentiated thyroid cancer (DTC) in 177 cases and 275 matched controls from the native population." (PMID 25849217, 2015). "The expression of ATM and γH2AX was detected by immunohistochemistry in 30 cases of benign nodular goiter, 110 cases of well differentiated thyroid cancer, 22 cases of poorly differentiated thyroid cancer, and 21 cases of anaplastic thyroid cancer." (PMID 25861265, 2015).
gastric adenocarcinoma (5 papers, 2020 to 2023). "Recently, in a cohort of 282 Chinese patients with gastric adenocarcinoma tested for germline variants in a panel of 69 cancer susceptibility genes, ATM PVs were the most common, with a prevalence of 1.1% in affected individuals." (PMID 37509701, 2023).
Hutchinson-Gilford progeria syndrome (5 papers, 2015 to 2025). "In addition, heterozygosity of p65/RelA in a mouse model of Hutchinson-Gilford Progeria Syndrome (Zmpste24-/-) resulted in attenuated aging pathology and a prolonged lifespan, linked in part to a reduced systemic inflammatory response and a reduction in ATM/NEMO-mediated NF-κB activation." (PMID 32201398, 2020). "For example, increased ATM phosphorylation and nuclear-localized NEMO were found in the Zmpste24-/- mouse model of Hutchinson-Gilford progeria syndrome (HGPS), where accumulation of nuclear prelamin-A leads to a perturbation of NF-κB signaling." (PMID 32201398, 2020).
lung disease (5 papers, 2020 to 2025). "Since a disturbed redox balance has been implicated in the pathophysiology of A-T lung disease, we aimed to further explore the interplay between ATM and oxidative stress in lung cells." (PMID 33338048, 2020). "Thus, our findings indicate that targeted inhibition of CXCR1/CXCR2 attenuates pulmonary phenotypes caused by ATM-deficiency and suggest that this treatment approach represents a viable therapeutic strategy for A-T lung disease." (PMID 33608602, 2021). "Other authors have hypothesized that ATM-deficient innate immune cells present an extended life due to altered DNA damage response, and could contribute to chronic inflammation, leading to the development of lung disease." (PMID 34065066, 2021). "Thus, our findings suggest that the ATM-deficiency perpetuates the impact of an initial lung injury by promoting a cycle of chronic inflammation and tissue damage that ultimately result in lung disease in A-T patients, including bronchiectasis and consolidation." (PMID 33608602, 2021). "Three patients had exposure to immunosuppressants for lung disease prior to the identification of their ATM variants, while the remaining 9 had no prior immunosuppression." (PMID 40179146, 2025).
metastatic melanoma (5 papers, 2015 to 2025). A melanoma that has spread from its primary site to another anatomic site. "Previous studies on nodular metastatic melanoma samples showed an upregulation of ATM at both transcript and protein levels." (PMID 26275218, 2015). "Consequently, ILF2‐U2AF2 promoted resistance to TMZ, but also enhanced the sensitivity to ATM inhibitor (ATMi) in metastatic melanoma." (PMID 34709752, 2021). "Also, our evidence from RPPA and in vitro assays indicated RAD50 and ATM proteins as downstream effectors of the ILF2‐U2AF2 complex in metastatic melanoma cells." (PMID 34709752, 2021). "Paradoxically, metastatic melanoma cells with ILF2‐OV were more sensitive to ATM inhibitors." (PMID 34709752, 2021). "Our results show that ILF2 and U2AF2 may have implications in RAD50 and ATM mRNA processing in metastatic melanoma." (PMID 34709752, 2021). "Our results demonstrated the regulatory role of ILF2 controlling the expression of RAD50 and ATM pathway activation, which consequently enhanced the efficiency of DDR by activating HR in metastatic melanoma cells." (PMID 34709752, 2021). "The upregulated ATM activation observed in ILF2‐OV cells could explain the ILF2‐induced effects on proliferation, resistance to DNA‐damage agents, and high efficiency of HR in metastatic melanoma cells." (PMID 34709752, 2021). "CYT-high metastatic melanomas had recurrent copy number amplifications in loci 1p12 (NOTCH2), 1q44 (OR2M4), 7q36.1 (KCNH2), 11q13.3 (FGF3/4), 12p11.23 (MED21) and 12q13.3 (R3HDM2) and deletions in 1p22.1 (RHOC, NRAS), 9p21.3 (CDKN2B), 10q23.2 (miR346), 11q23.3 (ATM, CHEK1, ETS1) and 15q15.3 (CASC4)." (PMID 33779796, 2021). "Consequently, RAD50 and ATM improve DDR and promote resistance to TMZ in metastatic melanoma." (PMID 34709752, 2021).
osteoporosis (5 papers, 2016 to 2025). A condition of reduced bone mass, with decreased cortical thickness and a decrease in the number and size of the trabeculae of cancellous bone (but normal chemical composition), resulting in increased fracture incidence. "Because a loss of ATM in osteoclasts results in enhanced bone resorption, it is tempting to speculate that the decrease in ATM activity is causally related to the pathogenesis of senile osteoporosis." (PMID 27677594, 2016). "Our results confirmed that QEP has a curative effect on osteoporosis in vivo and verified the involvement of ATM and the AKT/PI3K pathway in improving osteogenesis and inhibiting the ferroptosis of osteoblasts." (PMID 35865965, 2022). "However, the involvement of ATM/ATR and the relationship between RAD51 and ATM/ATR in osteoporosis remains unknown." (PMID 35176943, 2022). "The experiments validated that QEP exerted therapeutic effects on osteoporosis by inhibiting ferroptosis and promoting cell survival via the PI3K/AKT pathway and ATM." (PMID 35865965, 2022). "However, the role of RAD51 and its interaction with ATM/ATR in osteoporosis remains unclear." (PMID 35176943, 2022). "Furthermore, Qing e Pill (QEP) mitigates osteoblast apoptosis in primary osteoporosis via the ATM serine/threonine kinase (ATM) and PI3K/AKT pathways, thereby exerting its therapeutic effects on osteoporosis." (PMID 41551515, 2025).
ovarian tumor (5 papers, 2017 to 2025). "Beyond these mutations, germline or somatic aberrations in genes of the homologous recombination (HR) pathway such as RAD51B/C/D, PALB2, ATM, BRIP1 may confer an HR deficiency in up to 50% of ovarian tumors." (PMID 36531003, 2022).
primary immunodeficiency (5 papers, 2017 to 2025). "The combined assay has recently also been used to screen patients with SCID, ATM, Wiskott-Aldrich syndrome (WAS), DiGeorge syndrome, and trisomy 21, and it has been suggested to be included in routine screening of newborns for primary immunodeficiency." (PMID 27873105, 2017).
psoriasis (5 papers, 2013 to 2025). An autoimmune condition characterized by red, well-delineated plaques with silvery scales that are usually on the extensor surfaces and scalp. "A 2019 proteomic study identified SLFN5 among a set of new disease-associated proteins in psoriasis, alongside other markers (ATM, ZNF512, SPATA13, etc.)." (PMID 41328434, 2025).
rectal tumors (5 papers, 2013 to 2025). "This association was most evident from the inverse correlation between miR-18a and ATM in rectum tumor tissues (p<0.01)." (PMID 23437304, 2013). "ATM expression was evaluated in 45 pairs of rectal tumor and adjacent normal tissues." (PMID 23437304, 2013). "Further demonstrating its flexibility, the platform stratified survival outcomes by tumor subsites in ATM-mutant CRC, revealing potential differences between colon and rectal tumors." (PMID 40940961, 2025).
T-cell acute lymphoblastic leukemia (5 papers, 2015 to 2026). Acute lymphoblastic leukemia of T-cell origin. "Mice deficient in the ataxia telangiectasia mutated (ATM) kinase have impaired responses to genotoxic and oxidative stressors, predisposing them to develop thymic T-cell lymphoblastic lymphomas (T-LBL) resembling human T-cell acute lymphoblastic leukemias (T-ALL)." (PMID 39637056, 2024).
antibody deficiency (4 papers, 2020 to 2022). "A homozygous deleterious mutation in the ATM gene was identified, which together with his antibody deficiency, radiosensitivity, and neurological signs, established a diagnosis of A-T." (PMID 34686943, 2022). "The subclinical antibody deficiency in young patients with the A-T variant might become clinically apparent with progressive aging of the immune system due to the lack of ATM protection." (PMID 35154108, 2022). "Most patients in the ATM (92.5%) and STAT3 (AD-LOF) (89.5%) groups had similar clinical diagnoses, however, patients with DNMT3B/ZBTB24 mutations were first diagnosed with hypogammaglobulinemia (13, 68.4%), immunoglobulin A deficiency (2, 10.5%), and agammaglobulinemia (1, 5.3%)." (PMID 36544766, 2022).
autism spectrum disorder (4 papers, 2021 to 2023). A spectrum of developmental disorders that includes autism, and Asperger syndrome. "The altered AKT1-signalling pathway is also evident in ATM-associated autism spectrum disorders that may exaggerate COVID-1940." (PMID 36229517, 2022).
breast invasive carcinoma (4 papers, 2018 to 2023). "Interestingly, a positive correlation between ATM, ATR, BRCA1, BRCA2, and KMT2C expression is also derived from TCGA data GBM, LGG, AML, DLBL, SARC, and breast invasive carcinoma (BRIC) RNA‐seq data." (PMID 30665945, 2019).
chordoma (4 papers, 2018 to 2025). Chordomas are rare malignant tumors arising from embryonic remnants of the notochord in axial skeleton. "Genes central for module 2 (and thus probably important for functioning of chordomas in both clusters) were either responsible for cell division and DNA repair process (e.g. ATM, CHEK, BMI1, MDM2) or parts of inhibitors of apoptosis cascade (e.g. CASP2, CASP8, SIRT2)." (PMID 37434245, 2023).
chronic myeloid leukemia (4 papers, 2017 to 2022). "Our data demonstrated that Wee1 participated in promoting cell proliferation and imatinib resistance in chronic myeloid leukemia via regulating DNA damage repair dependent on ATM-γH2AX-MDC1." (PMID 36575478, 2022). "In chronic myeloid leukemia (CML), ATM was investigated as a potential candidate gene for the increased genetic instability following the evolution from chronic phase to blasts crisis (BC)." (PMID 28356161, 2017).
colloid carcinoma (4 papers, 2019 to 2023). "The one without concurrent KRAS mutation had a histological appearance of colloid carcinoma, with somatic ATM and APC mutation." (PMID 35180847, 2022). "In addition, mucinous (colloid) carcinomas are significantly more common than typical ductal carcinomas in patients with germline ATM mutations, further highlighting the link between mutations in this gene and IPMNs20." (PMID 32796935, 2020).
cyst (4 papers, 2017 to 2022). A sac-like closed membranous structure that may be empty or contain fluid or amorphous material. "As MDCK cells do not have mutations in PKD-causative genes, we further evaluated the effect of ATM inhibition in a human ADPKD cyst model using WT 9-12 cells, which possess a homozygous PKD1 variant." (PMID 33802342, 2021). "First, inhibition of either ATM or ATR reduced cyst growth in vitro in the MDCK cyst model, but the latter was associated with a dysplastic cystic phenotype." (PMID 33802342, 2021). "In vitro, pharmacological ATM inhibition by AZD0156 reduced three-dimensional cyst growth in MDCK and human ADPKD cells by up to 4.4- and 4.1-fold, respectively." (PMID 33802342, 2021). "We hypothesized that inhibiting ataxia telangiectasia mutated (ATM; a proximal DDR kinase) together with low-dose cisplatin overwhelms the DDR response and leads to selective apoptosis of cyst-lining epithelial cells (CECs)." (PMID 36293397, 2022). "This study focused on evaluating the functional role of ATM by initially assessing the efficacy of three well-characterized pharmacological inhibitors (KU-60019, AZD1390, and AZD0156) on cyst growth in vitro." (PMID 33802342, 2021). "Second, a clinically relevant ATM inhibitor, AZD0156, also reduced in vitro cyst growth using human ADPKD derived cells." (PMID 33802342, 2021). "Interestingly although AZD1390 is a more potent ATM inhibitor than AZD0156 (IC50 value of 0.78 vs. 0.58 nM), we found that the latter had greater efficacy in reducing cyst growth in vitro." (PMID 33802342, 2021). "Our results showed that while ATM kinase inhibition reduced cyst growth in vitro, the reduction of ATM by genetic ablation did not alter the progression of cystic kidney disease in a well-established murine genetic ortholog of ADPKD." (PMID 33802342, 2021).
endometriosis (4 papers, 2018 to 2021). The growth of functional endometrial tissue in anatomic sites outside the uterine body. "Herein, we discuss the role of key pathways like Mitotic roles of polo-like kinase, Role of CHK proteins in cell cycle checkpoint control, Aldosterone signaling in epithelial cells, and ATM Signaling in endometriosis progression." (PMID 32575462, 2020). "Indeed, expression levels of BRCA1, Rad51, and ATM in endometrial tissue proved to be lower in the endometriosis group than in control subjects, as were expression levels of BRCA1 and BRCA2 in ovarian tissue." (PMID 30622513, 2018).
Familial adenomatous polyposis (4 papers, 2018 to 2025). Familial adenomatous polyposis (FAP) is characterized by the development of hundreds to thousands of adenomas in the rectum and colon during the second decade of life.
Hepatic fibrosis (4 papers, 2019 to 2025). The presence of excessive fibrous connective tissue in the liver. "The absence of genotyping for ATM gene variants and the small number of patients with significant hepatic fibrosis are some limitations of the current study." (PMID 37147676, 2023). "Concomitantly, ATM was demonstrated to promote liver fibrosis." (PMID 31591327, 2019).
HIV-1 infection (4 papers, 2008 to 2013). The type species of lentivirus and the etiologic agent of acquired immunodeficiency syndrome (AIDS). "Altogether, these data indicate that the activation of ATM also occurs in vivo, in the brain, lymph nodes and circulating immune cells of patients with HIV-1 infection." (PMID 18560558, 2008). "The present study delineates a novel role of ATM in HIV-1 infection, in a pro-apoptotic signal transduction pathway that is independent of HIV-1 integrase, but dependent on the fusogenic action of Env." (PMID 18560558, 2008). "Thus, the ATM-dependent cellular pathway and Vpr-induced DNA damage are novel targets for preventing persistent HIV-1 infection." (PMID 23432899, 2013). "Thus, ATM inhibition might have a dual beneficial effect on HIV-1 infection, by inhibiting Env-elicited bystander killing and by triggering the apoptotic destruction of freshly infected cells." (PMID 18560558, 2008). "DNA damage foci containing phosphorylated ATM and H2AX were detectable in syncytia present in the brain or lymph nodes from patients with HIV-1 infection, as well as in a fraction of blood leukocytes, correlating with viral status." (PMID 18560558, 2008). "Based on these observations, we propose that the ATM-dependent mode of DSB-specific integration of viral DNA and the Vpr-induced DSBs are novel targets for anti-HIV compounds that inhibit viral transduction into MDMs, a persistent reservoir of HIV-1 infection." (PMID 23432899, 2013). "Although the GFP reporter assay indicated involvement of ATM and DNA-PKcs in HIV-1 infection consistent with previous reports, the sequence analyses of the host-virus junctions revealed that Mre11 and NBS1 were also involved in HIV-1 infection." (PMID 20003485, 2009). "The ATM-dependent mode of the DSB-specific viral DNA integration and Vpr-induced DSBs may be novel targets for anti-HIV compounds that inhibit viral transduction into MDMs, which are a persistent focus of HIV-1 infection." (PMID 23432899, 2013). "Combined with observations that Vpr activates ATM and ATR and that macrophages are resistant to DSBs compared with monocytes, our data suggest that the enhancement of IN-CA–independent viral transduction into MDMs may be a pivotal role of Vpr in HIV-1 infection." (PMID 23432899, 2013).